WT1 (WT1 transcription factor)
Diseases named in the same sentence as WT1 in open-access papers (continued):
Sharing a sentence is not in itself a finding about the gene and the disease.
anemia (8 papers, 2016 to 2025). A reduction in the number of red blood cells, the amount of hemoglobin, and/or the volume of packed red blood cells. "In the present study, we show that mice heterozygous for a knocked-in Wt1 R394W mutation can develop anemia with concomitant erythroid dysplasia, consistent with ineffective erythropoiesis and MDS." (PMID 30450160, 2018). "This loss of significance in the multivariate analysis suggests that the prognostic impact of WT1 may be confounded by other clinical variables, such as anemia and gender, which showed significant associations with survival in our cohort." (PMID 40507300, 2025). "Despite a persistently high vitamin B12 concentration, normal MCV, and increasing PLT, the patient’s anemia progressed, and her WT1 mRNA level increased." (PMID 39087180, 2024). "In this case study, replacement therapy temporarily improved anemia and suppressed WT1 mRNA expression, although both the symptoms subsequently recurred, became irreversible, and a new chromosomal abnormality was detected." (PMID 39087180, 2024). "Anemia is observed in recipients of all abnormal marrow genotypes, but not in wild type bone marrow recipients (mean hemoglobin, 8.64 ± 0.76 g/dL for Wt1+/R394W recipients, vs. 11.86 ± 1.11 g/dL for wild type, p = 0.03)." (PMID 30450160, 2018). "These important findings shed light on the potential beneficial role of WT1 in anemia." (PMID 35465313, 2022). "We conclude that the anemia in the Wt1+/R394W mice was of a primary hematologic etiology." (PMID 30450160, 2018). "The exact mechanism by which WT1 benefits anemia remains largely unknown." (PMID 35465313, 2022). "From the mechanism of action of HIF–PHIs, to cancer hypoxia and the biological significance of WT1, this review will discuss the link between HIF, WT1, anemia correction, and cancer." (PMID 35465313, 2022). "In conclusion, we demonstrate here that the presence of Wt1+/R394W in the murine hematopoietic system leads to the development of MDS with single lineage dysplasia, manifested as anemia and erythroid dysplasia, and contributing to a trend in decreased survival." (PMID 30450160, 2018). "Thus, although the MEPs are numerically expanded in the bone marrow of Wt1+/R394W mice, these competitive repopulation data suggest that the Wt1+/R394W MEPs are functionally abnormal, complementary to our finding that Wt1+/R394W mice develop MDS characterized by dyserythropoiesis and anemia." (PMID 30450160, 2018). "Based on these data, WT1 is a useful marker of disease and of response to JAK2 inhibitors especially for patients without blasts and for patients who develop anemia or thrombocytopenia not for progression but as therapy‐related toxicity." (PMID 27167495, 2016). "Furthermore WT1 is a good marker of response to JAK2 inhibitors especially for patients without blasts and for patients who develop anemia or thrombocytopenia not for progression but as therapy related toxicity." (PMID 27167495, 2016).
bladder cancer (8 papers, 2018 to 2025). "In this study, we demonstrated that combining an oral WT1 cancer vaccine using a Bifidobacterium vector and following anti-PD-1 antibody treatment eliminated tumor growth in a syngeneic mouse model of bladder cancer." (PMID 34589578, 2021). "In summary, our results provide evidence that GP73 can activate the TGF‐β1/Smad2 signalling pathway and induce the EMT via down‐regulating WT1 expression, thereby promoting the invasion and metastasis of bladder cancer." (PMID 29349903, 2018). "Combination of oral Wilms’ tumor 1 (WT1) cancer vaccine and anti-PD-1 antibody treatment using a Bifidobacterium vector has been shown to eliminate tumor growth in a syngeneic mouse model of bladder cancer." (PMID 36003378, 2022). "More recently, vaccination with WT1 peptide-loaded dendritic cells combined with targeted therapy or conventional chemotherapy demonstrated safety and feasibility in advanced RCC and bladder cancer patients." (PMID 38929778, 2024). "More recently, vaccination with WT1 peptide-loaded dendritic cells (DCs), coupled with targeted immunotherapy and/or traditional chemotherapy, was investigated in five RCC and five bladder cancer patients with relapsed or refractory disease." (PMID 35453662, 2022). "Bladder cancer cell lines (T24, 5637, RT4, 253J and J82) were selected and assigned to blank, negative control (NC), TGF‐β, thrombospondin‐1 (TSP‐1), TGF‐β1+ TSP‐1, GP73‐siRNA‐1, GP73‐siRNA‐2, GP73‐siRNA‐1+ TSP‐1, GP73‐siRNA‐1+ pcDNA‐GP73, WT1‐siRNA and WT1‐siRNA + GP73‐siRNA‐1 groups." (PMID 29349903, 2018).
breast tumors (8 papers, 2007 to 2020). "In breast tumours however, the WT1-expressing tumours are mainly associated with a mesenchymal phenotype and high levels of CYP3A4: therefore, their cells not only respond poorly to taxane, but they are also more likely to invade the blood vessels and metastasise." (PMID 28345629, 2017). "The methylation of three of them (ESR1, MGMT and WT1) has been widely reported in breast tumors." (PMID 22011321, 2011). "Wt1 presents a developmental pattern of expression in normal mammary gland, and changes observed in cell lines and tumors may be indicative of breast-tumor-related perturbations of Wt1 expression." (PMID 18062813, 2007).
Obesity (8 papers, 2015 to 2025). Accumulation of substantial excess body fat. "Collectively, these results indicate that multigenerational paternal obesity enhances the susceptibility of the offspring to spermatogenesis disorders by increasing METTL3-mediated Wt1 N6-methyladenosine modification." (PMID 38355624, 2024). "Mechanistically, treating the fathers with STM2457, a METTL3 inhibitor, restores obesity-reduced sperm count, and decreases Wt1 N6-methyladenosine level in the mouse testes of the offspring." (PMID 38355624, 2024). "Genetically, segmental deletions encompassing the WT1 and PAX6 genes are known to cause the syndromic phenotype, while an accompanying phenotype of obesity is linked to the extensive deletion involving the brain-derived neurotrophic factor (BDNF) locus." (PMID 29061165, 2017). "Overall, these studies report that adherence to a Mediterranean Diet and/or calorie restriction were associated with decreased DNA methylation in obesity-related genes such as PDK4, KCNQ1, WT1, SH2B1, FTO, BDNF, and PPARGC1A or inflammatory genes such as TNF-α." (PMID 31506096, 2019). "Untreated db/db mice exhibited obesity, progressive hyperglycemia, albuminuria, kidney hypertrophy and glomerular mesangial matrix expansion, increased renal production of fibronectin and a-smooth muscle actin, and decreased glomerular WT-1+-podocytes and nephrin expression." (PMID 39273597, 2024). "Wt1 heterozygosity reduced epididymal WAT mass, improved whole-body glucose tolerance and alleviated severe hepatic steatosis upon diet-induced obesity in mice." (PMID 34846543, 2022).
acute promyelocytic leukemia (7 papers, 2013 to 2024). An aggressive form of acute myeloid leukemia (AML), characterized by arrest of leukocyte differentiation at the promyelocyte stage, due to a specific chromosomal translocation t(15;17) in myeloid cells. "In AP-1060, an acute promyelocytic leukemia cell line derived form an adult patient, this can be explained by the fact that these cells harbor a homozygous deletion in the 11p13 locus, leading to bi-allelic loss of WT1 expression." (PMID 37444601, 2023). "Adding complexity to the idea that non-coding mutations can impact MYB binding sites and contribute to cancer, mutations in a cis-acting element in an intron of the WT1 gene were found to destroy MYB binding and downregulate the tumor suppressor gene WT1 in acute promyelocytic leukemia." (PMID 38542205, 2024). "The current study attempted to overcome this limitation by confirming the association between WT1 knockdown and reduced TERT expression in NB4, an acute promyelocytic leukemia cell line with known high levels of WT1 expression and HEK293 cells, a transformed human embryonic kidney cell line." (PMID 35406427, 2022). "We monitored WT1 decrement along the treatment course to identify its significant role as a marker for residual disease in acute promyelocytic leukemia (APL) and tried to suggest its significance for relapse prediction." (PMID 28114959, 2017).
adenosarcoma (7 papers, 2012 to 2025). A low grade malignant neoplasm characterized by the presence of a benign epithelial component (tubular and cleft-like glands) and a low grade sarcomatous component that contains varying amounts of fibrous and smooth muscle tissues. "Cluster of differentiation 10, WT1, ER, and PR are highly expressed in the sarcomatous component, among which ER and PR positivity is detected in about 50–80% of adenosarcomas." (PMID 38783282, 2024). "CD10 and WT1 may be crucial for the diagnosis of adenosarcomas." (PMID 24649216, 2013). "The most common immunohistochemical markers for the sarcomatous component of adenosarcomas are CD10 (71–100%), WT1 (79%), and vimentin (86%)." (PMID 32972432, 2020). "WT1, a tumor suppressor gene, was positive for adenosarcoma with or without sarcomatous overgrowth." (PMID 24649216, 2013). "Immunohistochemical analysis of adenosarcoma without sarcomatous overgrowth showed expression of CD10, WT1, ER, PR, androgen receptor (AR), cytokeratin and muscle markers." (PMID 24649216, 2013).
brain tumors (7 papers, 2010 to 2020). "It seems that WT1 expression in brain tumors depends on the tumor’s histopathologic entity more than its grade due to diversity of cellular origin or molecular profile." (PMID 32856872, 2020). "Here we review recent developments in the fields of Tet-dependent 5mC oxidation and WT1 biology and explore potential perspectives for studying the interplay between TETs and WT1 in brain tumors." (PMID 29623275, 2018). "Furthermore, we endeavour to perform CRISPR cas9 facilitated WT1 targeted knockout and subsequently implement next generation sequencing technologies to globally map 5caC genomic distribution and influence on brain tumour transcriptomes." (PMID 30405205, 2018).
clear cell sarcoma (7 papers, 2007 to 2025). A rare malignant neoplasm with melanocytic differentiation characterized by the presence of polygonal or spindle shaped clear cells. "Additional diagnostics such as immunohistochemical staining for the presence of cytokeratin, vimentin, desmin, actin, and WT1 allows distinguishing between other rare cancer types such as renal sarcoma, mesoblastic nephroma, clear cell sarcoma, or rhabdoid tumor." (PMID 34322362, 2021).
congenital nephrotic syndrome (7 papers, 2018 to 2025). "Second, we detected three congenital nephrotic syndrome (CNS) gene variants, NPHS2 (five cases), NPHS1 (two cases), and WT1 (one case) in eight patients with a mean age of 52 months." (PMID 39625990, 2024). "Most of the genes commonly associated with congenital nephrotic syndrome have reported ocular manifestations (NPHS1, NPHS2, WT1, LAMB2, PAX2, PLCE1)." (PMID 37578539, 2024).
cryptorchidism (7 papers, 2013 to 2025). The failure of one or both testes of a male fetus to descend from the abdomen into the scrotum during the late part of pregnancy. "While boys with germline WT1 mutation frequently present with urogenital malformation and cryptorchidism, girls are phenotypically normal and WT1 germline mutations are easily overlooked." (PMID 40340749, 2025). "Previous work has also verified the association between Wt1 and cryptorchidism using conditional gene inactivation in mice." (PMID 30137416, 2018). "Patients with rare germline mutations in WT1 have presented with cryptorchidism, the absence of testes from the scrotum." (PMID 30137416, 2018).
Hyperglycemia (7 papers, 2012 to 2025). An increased concentration of glucose in the blood. "In this study, hyperglycemia-induced podocyte injury is demonstrated as urine albumin leakage, foot process effacement and loss of podocyte markers, podocin and WT1." (PMID 22848482, 2012). "Hyperglycemia induces miR-193a, which downregulates WT1 and activates inflammatory pathways, contributing to podocyte damage." (PMID 41009556, 2025). "Consistently, WT1 positive podocytes decreased under hyperglycemia, which increased after TFP5 treatment." (PMID 35874807, 2022). "Merged nephrin and WT1 staining was also evident, and together, these results indicate that early hyperglycemia enhances podocyte injury in an IR-induced AKI model." (PMID 34561469, 2021). "Predominant detection of WT1 in diabetic patients and its almost complete absence in age matched non-diabetic controls may indicate early hyperglycemia-induced podocyte injury/remodeling in diabetic patients." (PMID 23544132, 2013).
Inguinal hernia (7 papers, 2015 to 2025). Protrusion of the contents of the abdominal cavity through the inguinal canal. "Jorgenson and colleagues previously identified 4 inguinal hernia susceptibility loci purported to result in reduced MMP activity: WT1, EFEMP1, EBF2 and ADAMTS6." (PMID 36584111, 2022). "We identified four novel inguinal hernia genetic susceptibility loci near the genes WT1, EFEMP1, EBF2 and ADAMTS6, and confirmed those associations in an independent cohort." (PMID 26686553, 2015). "Lastly, WT1, a gene highly expressed in mesothelial-like cells in our dataset and also present in hernia tissue from male patients, has been linked to inguinal hernia susceptibility in humans, further warranting additional investigation into the role of mesothelial-like cells in LAM fibrosis." (PMID 40504614, 2025). "We found variants at nine loci to associate with POP; five of which associate at genome-wide significance with POP, three that were previously associated with height (P < 1.4 × 10−5) at TXNDC5 (6p24.3), SLC12A2 (5q23.3) and LOXL1 (15q24.1) and one at WT1 that associates with inguinal hernia (11p13)." (PMID 32184442, 2020). "Comparatively, in males with inguinal hernia, WT1 rs3809060 GT/TT was found to be a genetic variation significantly correlated with inguinal hernia (OR: 1.17, 95% CI: 1.02-1.35, p = 0.02)." (PMID 37082733, 2023). "This hospital-based case-control study identified preferential SNPs with increased susceptibility to adult-onset inguinal hernia; EFEMP1 rs2009262 in females and WT1 rs3809060 in males, specifically in association with direct-type inguinal hernia." (PMID 37082733, 2023). "A greater prevalence of the EFEMP1 rs2009262 TC/CC genotype (36.6% vs. 32.6%, p = 0.01) and the WT1 rs3809060 GT/TT genotype (48.1% vs. 44.1%, p = 0.02) was found in the inguinal hernia group than in the control group." (PMID 37082733, 2023). "The WT1 rs3809060 locus exhibited an association with hernia risk among male participants, while overweight (BMI ≧ 24 kg/m2) males carrying the TC/CC genotype of the EFEMP1 rs2009262 variant were found to be at an increased risk of developing inguinal hernia." (PMID 37082733, 2023). "These loci for inguinal hernia susceptibility are EFEMP1, WT1, EBF2, and ADAMTS6." (PMID 31024927, 2019).
lung squamous cell carcinoma (7 papers, 2013 to 2025). "In addition, Moriya and his colleagues indicated that high level of WT1 was associated with the suppression of lymph node metastasis in patients with human lung squamous cell carcinoma (SCC)." (PMID 27821145, 2016). "WT1-pulsed dendritic cell (WT1-DC) therapy was performed for end-stage squamous cell lung cancer that rapidly worsened soon after completion of carboplatin and paclitaxel." (PMID 38022278, 2023). "Both WT1 and NY-ESO-1 are highly expressed in esophageal carcinoma, lung squamous cell carcinoma, and rectum adenocarcinoma." (PMID 31408937, 2019). "Therefore, we developed a Bi-TCRm-ADC (ESK-1G4-MMAE) against WT1 RMF/HLA-A*02:01 complex and NY-ESO-1 SLL/HLA-A*02:01 complex since the expression profiles of WT1 and NY-ESO-1 in tumor overlap partly, such as in esophageal carcinoma, lung squamous cell carcinoma, and rectum adenocarcinoma." (PMID 31408937, 2019).
malignant glioma (7 papers, 2018 to 2024). A grade III or grade IV glioma arising from the central nervous system. "This study showed that spontaneous IL-10 secretion and HTL epitope WT1-332-specific IL-10 secretion from PBMCs before vaccination were associated with a poor clinical prognosis in patients with recurrent malignant glioma treated with the WT1 Trio cancer vaccine." (PMID 36672344, 2023). "Positivity for skin reactions at injection sites remained high throughout the treatment course, demonstrating the feasibility and safety of WT1‐pulsed DC vaccination therapy in managing relapsed malignant gliomas." (PMID 39215399, 2024). "Here, we analyzed the association between immune-related factors before vaccination and clinical outcomes in patients with malignant glioma who received WT1 Trio once or more than once." (PMID 36672344, 2023). "In this phase I study, we evaluated first the safety and second the efficacy of WT1 peptide vaccine for patients with recurrent malignant glioma." (PMID 30430205, 2019). "The safety of a cocktail vaccine of WT1 HLA class I and II peptides for malignant gliomas was verified." (PMID 30430205, 2019). "In this article, we report on the safety of this cocktail vaccine for patients with recurrent malignant glioma, as well as on WT1-specific immunological responses and clinical outcomes." (PMID 30430205, 2019). "Notably, skin reactions at injection sites remained consistently positive throughout the treatment course, demonstrating the feasibility and safety of WT1‐pulsed DC vaccination therapy in managing relapsed malignant gliomas." (PMID 39215399, 2024). "However, WT1 has oncogenic functions and is overexpressed in leukemia and various types of solid tumors, including lung, colorectal, pancreatic, malignant gliomas, and bone and soft-tissue sarcomas." (PMID 36672344, 2023). "In a phase I trial, Wilms’ tumor 1 (WT1)-pulsed autologous DCs therapy showed safety and immunogenicity in the management of relapsed malignant gliomas." (PMID 35628161, 2022). "Finally, we analyzed the expression of p16, NGFR, WT1 and MME in 37 DIPG patient samples with H3.3K27M mutation and 58 non-brainstem pediatric high-grade glioma (NBS-HGG) samples with wild type H3.3 using the public database." (PMID 29932419, 2018). "(C) Box plot of gene expression levels of WT1 in DIPG with H3.3K27M (n = 37) and non-brainstem pediatric high-grade glioma (NBS-HGG) with wild type H3.3 (n = 58) tumor tissues." (PMID 29932419, 2018).